ZNF770 (zinc finger protein 770)
Description:
May be involved in transcriptional regulation.
Synonyms: FLJ20582; PRO1914
Tractability: PROTAC: UniProt records ubiquitination sites on it; ubiquitination databases record sites on it.
Gene: Protein-coding gene on chromosome 15 (34,978,341 to 34,989,479, reverse strand). Ensembl gene ENSG00000198146.
Subcellular location: Nucleus
Subcellular location (Human Protein Atlas): Nucleoplasm; Cytosol
Pathways (Reactome):
Gene expression (Transcription): Generic Transcription Pathway
Gene Ontology:
Molecular function: transcription cis-regulatory region binding
Biological process: regulation of transcription by RNA polymerase II
Cellular component: nucleus
Genetic constraint (gnomAD): Loss-of-function variants: 15 observed, 54.76 expected, observed/expected ratio (o/e) 0.27, 90% interval 0.18 to 0.42. The upper end of that interval is the gene's LOEUF score, 0.42, which puts it in group 1 of 6, group 1 being the genes least tolerant of losing a copy. Missense variants: 681 observed, 829.23 expected, observed/expected ratio (o/e) 0.82, 90% interval 0.77 to 0.88. Synonymous variants: 304 observed, 282.94 expected, observed/expected ratio (o/e) 1.07, 90% interval 0.98 to 1.18.
Homologues: Orthologues: chimpanzee ZNF770 (99% identical), macaque ZNF770 (98% identical), dog ZNF770 (82% identical), pig ZNF770 (81% identical), rabbit ZNF770 (81% identical), mouse Zfp770 (76% identical), rat Zfp770 (75% identical), Drosophila melanogaster hb (12% identical), Drosophila melanogaster CG12391 (8% identical), Caenorhabditis elegans Y5F2A.4 (8% identical), zebrafish plagl2 (7% identical), zebrafish ovol1b (7% identical), and 4 more. Paralogues in human: PEG3 (14% identical), ZSCAN5B (12% identical), ZSCAN5A (12% identical), ZNF274 (12% identical), ZSCAN5C (12% identical), REST (12% identical), ZKSCAN2 (12% identical), ZNF518A (12% identical), ZSCAN29 (11% identical), ZSCAN32 (11% identical), ZNF202 (11% identical), ZNF18 (11% identical), and 17 more.
Diseases named in the same sentence as ZNF770 in open-access papers:
ZNF770 is named in the same sentence as 5 diseases in open-access papers, as found by Europe PMC text mining. Sharing a sentence is not in itself a finding about the gene and the disease. The quoted sentences say what the papers report.
breast carcinoma (1 paper, 2024). "Motif discovery identified motifs associated with three transcription factors—EBF1, ZNF770, and PATZ1—suggesting potential regulatory mechanisms influencing gene expression and breast cancer intrinsic subtypes." (PMID 39452108, 2024).
colon cancer (1 paper, 2025). "Thus, SALL4 and ZNF770 transcription was inversely correlated with 5hmC levels during progression from normal to primary colon cancer to liver metastasis." (PMID 40241172, 2025).
cancer (2 papers, 2024 to 2025). A tumor composed of atypical neoplastic, often pleomorphic cells that invade other tissues. "Future functional analyses will reveal whether ZNF770 and ZNF121 have binding affinities for 5hmC or 5mC and whether they interact with TET enzymes to regulate 5hmC accumulation in normal tissue or cancers." (PMID 40241172, 2025).
tumour (1 paper, 2025). "Liver metastasis tends to have lower expression of SALL4 and ZNF770 compared to the primary tumours." (PMID 40241172, 2025). "In our study, ZNF770 transcript levels were inversely correlated with 5hmC levels in the primary tumour and metastasis." (PMID 40241172, 2025). "PAX5 transcripts are present at very low levels in normal tissue and are further reduced in tumours, whereas SALL4, ZNF770 and ZNF121 transcripts are upregulated in primary and metastatic tumours compared to normal colon." (PMID 40241172, 2025).
ZNF770 also shares sentences with these, for which no sentence is quoted: colorectal cancer (1 paper).